BCR (BCR activator of RhoGEF and GTPase)
Diseases named in the same sentence as BCR in open-access papers (continued):
Sharing a sentence is not in itself a finding about the gene and the disease.
leukemia (continued). "Various studies have excluded a role for BCR-ABLp210 expression in maintaining the population of leukemia stem cells." (PMID 36362357, 2022). "Studies have shown that reducing the BCR-ABL expression can inhibit the proliferation of leukemia cells." (PMID 35782508, 2022). "The fusion protein BCR-ABL is produced by the Philadelphia chromosome translocation found in leukemia." (PMID 36338985, 2022). "The resulting chimeric protein, BCR::ABL1, is a potent tyrosine-kinase signalling protein that drives cell proliferation and reduces apoptosis, which causes leukaemia." (PMID 35884363, 2022). "PB leukemia cells (GFP+B220+) for the recipient mice was monitored on days 15, 18, 22, 25 and 29 post BMT, the percentage and total number of leukemia cells was significantly lower in BCR/ABL1-Rora group recipients." (PMID 35414788, 2022). "Consistently, the protein and mRNA detection showed that the RanBP3 levels in CML cells (BCR-ABL+) were much higher than that of other leukemia cells (BCR-ABL-)." (PMID 34504783, 2021). "To identify novel compounds that target BCR–Abl-driven leukemias, we developed an isogenic cell competition–based drug screen by stably transfecting Ba/F3 cells with BCR–Abl." (PMID 33303632, 2021). "This and our recent reports highlight how distinct mechanisms of miR-126 dysregulation driven by specific leukemogenic mutations (i.e., CBFB-MYH11, BCR-ABL, FLT3-ITD) play a relevant role in leukemia pathobiology." (PMID 34686664, 2021). "Preclinical studies have shown that venetoclax is active for leukemias in the high-risk genetic group, such as KMT2A-rearranged ALL, hypodiploid ALL, BCR/ABL-positive ALL, TCF3/HLF-rearranged ALL, and T-ALL (including ETP-ALL)." (PMID 33946897, 2021). "On the other hand, leukemias involving the BCR-ABL fusion gene, present in about 4% of children with ALL, are characterised by a high incidence of relapses, whereas leukemias involving the TEL-AML1 fusion are associated with a good prognosis." (PMID 34944093, 2021). "It is important to note that for LSCs from the BCR–ABLp210 transgenic mice that DNA methylation at CpG islands is deregulated and that this is sufficient to give rise to leukemia." (PMID 34575830, 2021). "It was later discovered that constitutive activation of ABL1 upon fusion with the breakpoint cluster region (BCR) generated the BCR-ABL1 oncoprotein responsible for driving several forms of human leukemia." (PMID 34022881, 2021). "When calculating the SI value of leukemia cells or transfected Ba/F3 cells with the oncogene BCR/ABL, we found that MeST has a high selective effect on abnormal cells." (PMID 34068907, 2021). "The depletion of USP25 mediated by shRNA increases ubiquitinated BCR-ABL, which can promote the degradation of BCR-ABL protein in Philadelphia (Ph)-positive leukemia cells." (PMID 34249948, 2021). "The pathological mechanism of CML is generally understood as it is dependent on one dominant gene fusion, BCR-ABL, whereas each of the other leukaemias are more complex as their mutations occur in many different genes." (PMID 33709075, 2021). "The results showed that the SI values of MeST were higher than 3, indicating that the MeST had potent cytotoxic activity and good selectivity against leukemia cells with BCR/ABL." (PMID 34068907, 2021). "In our study, we found NOTCH2, FANCA, BCR, and ROS1 were significantly mutated in 109 Chinese patients with leukemia." (PMID 32638549, 2020). "And the BCR-ABL fusion gene (BCR-ABL) is another oncogenic factor of leukemia which exhibits different subtypes with discrepant prognosis." (PMID 32863957, 2020). "Gene targeting experiments have addressed the roles of BCR-ABLp190 and BCR-ABLp210 in the genesis of leukaemia." (PMID 32213936, 2020). "To further study the consequences of ruxolitinib on leukemia cells in vivo, we injected human BCR-ABL+ ALL cells into NSG mice and monitored the recipient mice under imatinib, ruxolitinib, or combined imatinib/ruxolitinib treatment." (PMID 32581241, 2020).
leukemia (continued). "Because the growth of disease was slower and median survival times in females were longer than in males, we determined the sex of the murine BCR-ABL leukemia cells using a PCR assay to discriminate X and Y chromosome-specific genes in the leukemia cells." (PMID 32047189, 2020). "IGF1R plays a role in differentiation of hematopoietic cells and appears to regulate BCR–ABL leukemia cell fate and self-renewal in chronic myeloid leukemia (CML) cells." (PMID 31980503, 2020). "Fusion of ABL1 to BCR/TEL/NUP214 is observed in a large number of leukemia patients and allosteric stimulation of the normal ABL1 kinase activity enhanced the antileukemia effect of ABL1 tyrosine kinase inhibitors." (PMID 31537905, 2020). "Chronic myeloid leukocyte (CML) is characterized by the Philadelphia (Ph) chromosome with fusion protein breakpoint cluster region-Abelson murine leukemia (BCR-ABL) tyrosine kinase overexpression." (PMID 32164715, 2020). "Mutational analysis was used to map the genetic variants in leukemia, and found that the highest mutations occurred in PDE4DIP, followed by NOTCH2, FANCA, BCR, and ROS1 in almost all leukemia patients." (PMID 32638549, 2020). "To further assess the relative leukemia burden at the primary sites of leukemia replication such as bone marrow and spleen, we quantified the number of luciferase-tagged BCR-ABL cells in the bone marrow." (PMID 32047189, 2020). "Within the B-ALL molecular subtypes, IL7R expression values were higher in the BCR/ABL1, ETV6/RUNX1, TCF3/PBX1, and KMT2A(MLL) high-risk leukemia subtypes." (PMID 32085659, 2020). "A comparable situation was found in murine leukemia cell lines transformed by the v-ABLp160+ or BCR-ABL1p185+ oncogenes." (PMID 31628323, 2019). "Leukemia latency of BCR-ABL1p185+ and v-ABLp160+ transformed Cdk8Δ/Δ cells was significantly increased compared to wild-type cells." (PMID 31628323, 2019). "Immunoprecipitation results showed that FAM168A interacts with breakpoint cluster region (BCR) -Abelson murine leukemia (ABL1) fusion protein and AKT1, respectively." (PMID 31291942, 2019). "Produced as a result of the Philadelphia chromosome, variants of the BCR-ABL gene fusion exist with alternative fusion points in either gene, which can be found in various leukemias." (PMID 31105873, 2019). "A sustained and total inhibition of BCR-ABL was evident when leukemia cells were treated with HC-NPs." (PMID 31510037, 2019). "BCR2 and BCR4 both have amplified loci in K652 cells, a leukemia cell line containing the BCR-ABL fusion, which indicates that they fall between the amplification unit of ABL locus on the Philadelphia chromosome." (PMID 31105873, 2019). "For example, the BCR-ABL and BCR-ABLp210 oncogenes have roles in human leukemia and initiate leukemia when the expression of each oncogene is restricted to HSCs in transgenic mice." (PMID 31275935, 2019). "Concerning metabolic substrates, Martina Poteti showed that glutamine availability suppressed the expression of oncoprotein BCR/Abl in leukemia stem cells, rendering them resistant to BCR/Abl tyrosine kinase inhibitors." (PMID 30338239, 2018). "Pre-BCR+ leukaemia blasts are further characterised by a constitutive activation of the PI3K-AKT signalling pathway and SRC kinase, as well as a downregulation of STAT5 activity." (PMID 28819864, 2018). "Clinical targeting of BCR-ABL gene, formed by the fusion of ABL gene from chromosome 9 to the BCR gene on chromosome 22, also called the Philadelphia chromosome, improved the clinical management of leukemia patients." (PMID 29455673, 2018).
leukemia (continued). "Encouragingly, both inhibitors led to a significant decrease in colony-forming activity in vitro and increased the survival in vivo, with pre-BCR+ leukaemia cells being more sensitive to A-770041 and P505-15 compared with pre-BCR− leukaemia cells." (PMID 28819864, 2018). "RhoGEF and GTPase activating protein (BCR), in turn, is one of the two genes involved in the BCR‐ABL complex associated with the Philadelphia chromosome in leukemias." (PMID 30108113, 2018). "Successful therapies have been developed to directly target several fusion proteins involved in signal transduction, such as BCR-ABL in leukemia and EML4-ALK1 in lung carcinoma." (PMID 30373318, 2018). "17-allylamino-17-demethoxygeldanamycin (17-AAG) was the first Hsp90 inhibitor which entered in the clinical trial for BCR/ABL (Breakpoint Cluster Region/Abelson)-positive leukemia or HER2/NEU+ (Human Epidermal growth factor Receptor 2) breast cancer." (PMID 29890785, 2018). "Clearly, it was of interest to examine the possible role of Gadd45b in modulating BCR-ABL driven leukemia." (PMID 30279966, 2018). "Altogether, these analyses revealed a dysregulation of CKS expression in MLLr leukaemia, but also in BCR-ABL positive CML, consistent with putative roles for CKS1B and CKS2 in leukaemogenesis." (PMID 28939057, 2018). "In BCR/ABL+ human leukemia cells, the activation of JNK signaling was coordinated with ERK signaling in apoptosis induced by an histone deacetylase inhibitor." (PMID 28806729, 2017). "These leukemia cells also displayed a similar lineage marker expression profile to that of Hoxa9+BCR/ABL and Hoxa10+BCR/ABL leukemia cells and were transplantable." (PMID 29228732, 2017). "Here, we observed the ability of NOX-A12 to potentiate the effects of ABL inhibition against BCR-ABL-positive leukemia in vitro and in vivo." (PMID 29299123, 2017). "Our results also suggest that Hoxa9 is more potent than Hoxa10 in inducing CML myeloid blast crisis, as the Hoxa9+BCR/ABL mice developed leukemia with a significantly shorter latency than Hoxa10+BCR/ABL mice." (PMID 29228732, 2017). "Although the relative BCR is demonstrated to act as a tumor suppressor in leukemia, a specific function of ABR in myelopoiesis and leukemia has not been addressed." (PMID 29262589, 2017). "As STAT5 plays a key role in the initiation and maintenance of BCR-ABL mediated leukemia, we performed a more detailed analysis in this context." (PMID 28753604, 2017). "In BCR/ABL1+ leukaemia, PAK1 and PAK2 are upstream regulators of the transcription factor STAT5 – a key node for initiation and maintenance of disease." (PMID 28707321, 2017). "In conclusion, our results provide evidence that SPOA has potent anti-leukemia activity in vitro and in vivo by specifically dephosphorylating and degrading BCR-ABL oncoprotein." (PMID 27926512, 2017). "Again, none of the recipient mice for GMPs singly infected with Hoxa10 or BCR/ABL virus developed leukemia." (PMID 29228732, 2017). "Here we report that oridonin inhibits the growth of Ph+ leukemia cells in vitro and in vivo by targeting BCR-ABL for degradation." (PMID 28128329, 2017). "The activities in BCR-ABL signal pathway in leukemia cells treated by 0.25μM Givinostat were studied at various post-treatment time points and demonstrated in Western blots." (PMID 28050230, 2016). "Western blotting showed the protein level of YAP was much higher in BCR/ABL+ leukemia cell lines than that in BCR/ABL− ones." (PMID 27599610, 2016). "Next, we determined the expression of YAP in BCR/ABL+ leukemia cell lines (K562, KCL22 and K562/G01) and BCR/ABL− cell lines (HL60, NB4 and THP1)." (PMID 27599610, 2016). "Therapies such as Trastuzumab for HER2-positive breast cancer, and Imatinib for leukemias driven by the BCR-ABL fusion are now widely used in clinical practice." (PMID 27526105, 2016).
leukemia (continued). "Unfortunately in advanced Ph+ leukemia, CML-blast crisis and Ph+ ALL, these TKI select resistant clones, mostly due to the presence of point mutations in BCR/ABL." (PMID 27014420, 2016). "Tonic pre-BCR signaling is necessary for leukemia cell survival in BCP-ALL (mainly TCF3-PBX1) expressing a pre-BCR." (PMID 27611867, 2016). "On the other hand, some studies have shown that STAT3 can enhance NK-mediated immunosurveillance, specifically in a model of BCR/Abl-dependent leukemia." (PMID 27148255, 2016). "The uptake of verteporfin by the primary cells of CML, another leukemia developed by BCR-ABL, is greater than that by the normal mononuclear cells of peripheral blood and bone marrow, which further explains their co-operation in vivo." (PMID 27494842, 2016). "In contrast to the CML-like disease the p96ABL/BCR and p185ABL/BCR induced lymphoid-like leukemia was re-transplantable, giving origin to a full blown leukemia within 38–60 days." (PMID 25919613, 2015). "Another report further highlights the utility of targeting CK2 in the setting of BCR-ABL-mediated leukemias and in particular p190-BCR-ABL ALL cells." (PMID 26843864, 2015). "IGF-IR regulates the cell fate determination of BCR/ABL+ leukemia cells and supports the self-renewal of CML cells." (PMID 25648584, 2015). "Here, we review the role of BCR-ABL/protein kinase CK2 interaction in BCR-ABL leukemias, with potentially relevant implications for therapy." (PMID 26843864, 2015). "We therefore used a retroviral BCR-ABL transplantation mouse model to further study the role of IGF-IR in regulation of BCR/ABL leukemia development." (PMID 25648584, 2015). "Although these data did not shed light on the complex mechanism of CK2 regulation, it is clear that BCR-ABL is able to force CK2 to modulate proliferation/survival in Ph+ leukemias." (PMID 26843864, 2015). "The presence of ABL/BCR changed the phenotype of the leukemia most likely due to its capacity to influence the stem cell population as shown by our in vivo data." (PMID 25919613, 2015). "Although IGF-IR is dispensable for normal HSC maintenance, it is critical to BCR/ABL leukemia fate determination." (PMID 25648584, 2015). "Although IGF-IR is dispensable for activity of normal HSCs, it is critical to BCR/ABL leukemia fate determination and self-renewal of CML cells." (PMID 25648584, 2015). "There have been many reports to study the function of the BCR-ABL translocation in many leukemia models, however this section will focus on the work that pertains to studies of ALL in BCR-ABL model systems." (PMID 24847444, 2014). "We then treated mice xenografted with Ph+ leukemia cells with the FAK inhibitor TAE226 in combination with a BCR–ABL TKI nilotinib." (PMID 24860788, 2014). "Using real-time monitoring of microimpedance, we studied in detail the kinetics of interaction of human CML cells (JURL-MK1, MOLM-7) and of control BCR-ABL-negative leukemia cells (HEL, JURKAT) with fibronectin-coated surface." (PMID 25198091, 2014). "The high-risk genetic aberrations such as mixed lineage leukemia (MLL) gene rearrangements with chromosome 11q23 abnormality and the Philadelphia chromosome (BCR/ABL) were detected in 3 infants (3/45; 6.7%) and in 4/45 (8.8%) cases, respectively." (PMID 23849470, 2013). "To extend the mouse model to human leukaemia, we first used K562, which is a BCR-ABL positive cell line derived from a CML patient in blast crisis and are resistant to most forms of chemotherapy." (PMID 23341130, 2013). "It is well known that abnormal fusion proteins resulting from chromosomal translocations can serve as relative leukemia-specific CTL response targets including the BCR-ABL and PML-RARα fusion proteins." (PMID 23394714, 2013).
leukemia (continued). "In the present study, we demonstrate that PECAM-1 is tyrosine phospho rylated in its ITIM motifs in various BCR/ABL-expressing cells including primary leukemia cells." (PMID 23233201, 2013). "Given the fact that all AKIs fail to inhibit BCR/ABL harboring the ‘gatekeeper’ mutation T315I, we investigated the effects of AKIs in combination with the allosteric inhibitor GNF2 in Ph + leukemia." (PMID 22985168, 2012). "The BCR-ABL fusion peptide is the predominant antigen in CML, and WT1 is also thought to be important for the identification of leukemia-associated antigens (LAAs) in CML to elicit a specific immune response in patients." (PMID 23241263, 2012). "In contrast, our results show that IRF4 behaves like a classical tumor suppressor, downstream of pre-BCR signaling, that functions to inhibit c-Myc induced leukemia." (PMID 21818355, 2011). "Dormant leukemia cells were collected from the spleen at these different times, and the amount of BCR/ABL mRNA quantitatively assayed using real-time PCR, leading to the following cell lines: DA1-3b/d35, DA1-3b/d90 and DA1-3b/d365." (PMID 21884581, 2011). "We think that B-NHEJ activity in BCR/ABL-positive leukemia cells is very intense, when compared to normal cells." (PMID 21637496, 2010). "Inhibition of ATR by caffeine or Chk1 by the indolocarbazole inhibitor SB218078 sensitized BCR/ABL leukemia cells to MMC in clonogenic assays." (PMID 27713304, 2010). "The use of checkpoint inhibitors in combination with MMC was investigated in a study of BCR/ABL-positive leukemia cells." (PMID 27713304, 2010). "Imatinib mesylate, which is a competitive inhibitor of certain tyrosine kinases including intracellular kinases ABL and the BCR-ABL fusion proteins present in some leukemias, and PDGFRA, is the first effective drug for GIST [, 18]." (PMID 17540038, 2007). "According to the break within the Bcr locus, three oncogenic BCR-Abl fusion proteins: p190, p210 and P230 can be formed and they all were found to be sufficient to generate leukaemia in humans and murine models." (PMID 15494718, 2004). "Additionally, the persistence of leukemia stem cells (LSCs), which are inherently less dependent on BCR::ABL1 signaling and often quiescent, presents a key therapeutic challenge." (PMID 41510882, 2026). "Additionally, combining PD-L1 mAb with nilotinib, a tyrosine kinase inhibitor (TKI), significantly improved survival of BCR::ABL+ leukemia-bearing mice." (PMID 40503229, 2025). "Several reports indicate that inhibition of autophagy may be a promising approach for the treatment of BCR::ABL1-mediated leukemia." (PMID 40113750, 2025). "Dasatinib and ponatinib are broad-spectrum TKIs used for the treatment of BCR::ABL+ leukemia." (PMID 41477551, 2025). "Although best known for its fusion with ABL1 in leukaemia, recent studies suggest that BCR overexpression may also promote breast tumour progression through modulation of MAPK signalling pathways." (PMID 40813389, 2025). "The tyrosine kinase encoded by the BCR/ABL fusion gene can continuously activate downstream signaling pathways (such as RAS, PI3K/AKT), leading to abnormal proliferation of leukemia cells and thus a significant increase in peripheral blood white blood cell counts." (PMID 41195225, 2025). "Allogeneic or autologous anti-leukemia CTL directed against minor histocompatibility antigens or the BCR/ABL neoantigen, have been successfully employed to treat relapsed leukemia in adult patients representing proof of principle for the potential efficacy of this form of T cell therapy." (PMID 40547030, 2025).